ITPR1 (inositol 1,4,5-trisphosphate receptor type 1)
Diseases named in the same sentence as ITPR1 in open-access papers (continued):
Sharing a sentence is not in itself a finding about the gene and the disease.
Ataxia (continued). "LoF mutations in ITPR1, encoding IP3R type 1, cause Gillepsie syndrome (GLSP), characterized by muscular hypotonia, mydriasis, ataxia, and intellectual disability, and Itpr1-null mice manifest severe ataxia and epileptic seizures." (PMID 33250786, 2020). "Homozygous ITPR1 knockout mice, which are deficient in cytosolic IP3-mediated Ca2+ release, display diminished LTD, severe ataxia and tonic-clonic seizures, resulting in death by weaning age." (PMID 32765211, 2020). "Loss of IP3R function in the vertebrate nervous system leads to defects in motor coordination and spino-cerebellar ataxia (SCA); a deletion mutation of ITPR1 in human causes SCA15/16, and the mouse knock out (KO) for Itpr1 displays ataxia." (PMID 28473752, 2017). "The affected proteins/disorders included Atp2a2 (Darier’s disease), Eef2 and Itpr1 (Spinocerebellar ataxia), Atp1a3 (Dystonia Parkinsonism)." (PMID 28893375, 2017). "Heterozygous large segmental deletions of ITPR1 were first identified in an Australian and two Belgium families with adult-onset, very slowly progressive, pure cerebellar ataxia that was designated as spinocerebellar ataxia (SCA) type 15 (SCA15; MIM #606658)." (PMID 29186133, 2017). "Signs of possible limbic involvement (confusion, severe memory loss, suspected temporal lobe epilepsy) were also present in two recent ITPR1-IgG-positive patients identified by the authors, one of whom also had cerebellar ataxia (unpublished data)." (PMID 27776522, 2016). "Recently, we described a novel autoantibody, anti-Sj/ITPR1-IgG, that targets the inositol 1,4,5-trisphosphate receptor type 1 (ITPR1) in patients with cerebellar ataxia." (PMID 27776522, 2016). "So far, only four patients with anti-Sj/ITPR1 have been published, all of whom had cerebellar ataxia; however, we have identified another eight (as yet unpublished) cases in the meantime." (PMID 26377085, 2015). "A success story for this approach is the identification of a new EA candidate gene, UBR4, which was selected as a candidate gene due to its role in ubiquitination and localization with another ataxia gene, ITPR1." (PMID 25055202, 2014). "Gardner suggests that SCA15/16 in humans found to have actual mutations in ITPR1, the gene that encodes the IP3R1 protein, be termed ITPR1-associated ataxia." (PMID 22703638, 2012). "Itpr1 also plays an important role in embryonic development; the majority of Itpr1 null mice die prenatally and those which survive to birth display severe ataxia and epilepsy." (PMID 22986007, 2012). "Interestingly, some cases corresponded to channelopathies associated with cognitive and motor delay, in which ataxia has also been described, including KCNC3, ITPR1, ATP1A3 and CTNNB1." (PMID 39048885, 2024). "ITPR1 gene mutations have long been recognized to cause non-progressive cerebellar ataxia and delayed motor development, known as SCAs (especially SCA 15 and 29) and GLSP." (PMID 39011359, 2024). "In humans, ITPR1 is considered a hub gene for cerebellar ataxias." (PMID 37964426, 2024). "Mice with a Purkinje neuron specific deletion of Itpr1 display progressive ataxia." (PMID 35757096, 2022). "Symptoms of cerebellar ataxia, either alone (N = 2) or in combination with other symptoms (N = 9), were present in 11/21 (52%) ITPR1-IgG/anti-Sj-seropositive patients, including limb ataxia with dysmetria, dysdiadochokinesis, intention tremor, gait ataxia, dysarthria, and gaze disturbances." (PMID 35907972, 2022). "Thus, in the double-mutant cerebellum, widespread abnormalities occur, involving a notable cohort of critical neuroregulatory genes including Itpr1, Grid2, and Ca8, whose perturbation in humans underpin ataxia syndromes." (PMID 34910524, 2021). "Mutations in genes encoding the neuronal isoform of the inositol 1,4,5-trisphosphate receptor (ITPR1) and genes involved in inositol 1,4,5-trisphosphate receptor degradation (ERLIN1, ERLIN2) are known to cause hereditary spastic paraplegia (HSP) and cerebellar ataxia." (PMID 31636353, 2019).
Ataxia (continued). "No repeat expansions in ITPR1 have been associated with cerebellar ataxia previously and this is the first reported naturally occurring pathogenic intronic repeat expansion in a non-human species." (PMID 25354648, 2015). "This represents the first naturally occurring pathogenic repeat expansion of its type in a non-human species and a novel mechanism for ITPR1-associated spinocerebellar ataxia." (PMID 25354648, 2015). "Mutations of ITPR1 have previously been implicated in spinocerebellar ataxia with and without cognitive decline." (PMID 25498830, 2014). "We describe two families with AD congenital nonprogressive spinocerebellar ataxia caused by missense mutations in ITPR1, demonstrating for the first time clinical heterogeneity associated with alterations of this gene." (PMID 22986007, 2012). "Serum ITPR1-IgG/anti-Sj titres in the present patient were clearly positive (1:1000, 1:320, 1:100, respectively) but lower than those reported in two of the three index patients with cerebellar ataxia and two of the three patients with neuropathy described in Ref." (PMID 35907972, 2022). "Homozygous, compound heterozygous and heterozygous mutations in ITPR1 could also cause Gillespie syndrome, which features a non-progressive cerebellar ataxia, aniridia, congenital hypotonia, and intellectual sub-normality (MIM #206700)." (PMID 29186133, 2017). "In contrast, ITPR1, PTPN1, SPTBN2, and WDR81 are known as cerebellar ataxia-related genes, and there is limited evidence of shared mechanisms with epilepsy." (PMID 37645600, 2023). "This includes conditions like anti-GAD Stiff-person syndrome or anti-Sj/ITPR1 and anti-NMDA cerebellar ataxia." (PMID 38983056, 2023). "Furthermore, ITPR1 mutation in humans can cause Gillespie syndrome or ataxia, while in our HM family no ataxia can be observed, suggesting that ITPR1’s function in the central neural system may be complemented by other ITPR family members or pathways." (PMID 33747042, 2021). "This is indeed the case for ITPR1, for which recessive and dominant de novo mutations causing Gillespie syndrome, a rare variant form of aniridia characterized by non-progressive cerebellar ataxia, intellectual disability and iris hypoplasia, have been described." (PMID 30148849, 2018). "A knockout of the Itpr1 gene in mice results in very early lethality, severe ataxia, and epileptic seizures without an overt cellular phenotype." (PMID 37964426, 2024). "Mutations in genes encoding for IP3R, for example inositol 1,4,5-trisphosphate receptor type 1 (ITPR1), have been reported in infantile-onset nonprogressive spinocerebellar ataxia (SCA)." (PMID 35098253, 2021). "Unlike human SCA15 cases, however, ataxia has not been observed in heterozygous dogs, perhaps because more ITPR1 transcript is produced than in haploinsufficient human cases." (PMID 25354648, 2015). "For example, tough mutated ITPR1 caused GLSP in humans, which typically manifests as craniofacial deformation, aniridia, and ataxia, but aniridia has never been observed in zebrafish, which possess the ITPR1b that is homologous to human ITPR1 and closely related to craniofacial bone formation." (PMID 39011359, 2024). "Therefore, we can assume that changes in the amino acid structure of ITPR1 may indirectly affect the activity of VCP or ATXN3, which may contribute to the development of a neurodegenerative process in this type of ataxia." (PMID 26770814, 2016). "However, we have termed a subset of ataxias, not just with reduced IP3R1 but also with supersensitive IP3R1, and regardless of the mutated gene (e.g., ITPR1, Ataxin-1, Ataxin-2, Ataxin-3) as ‘IP3R1-associated ataxias’." (PMID 22703638, 2012). "Interestingly, among the 24 PC genes with restored expression, seven genes (Abr, Calb1, Htr1b, Itpr1, Kcnip1, Kcnma1, and Mtss1) were part of a group of 80 PC-type-specific downregulated genes common to the SCA1, SCA2, and SCA7 mouse models and composed an ataxia molecular signature." (PMID 38673939, 2024).
Ataxia (continued). "Mutations localized in the coupling/regulatory domain of IP3R1, such as ITPR1 p.P1068L (originally annotated as p.P1059L, reference sequence NM_002222), might affect the binding affinity and transmission of the IP3 signaling which further disrupts the calcium influx, resulting in cerebellar ataxia." (PMID 29186133, 2017).
breast carcinoma (29 papers, 2014 to 2026). "Lower expression of ITPR1 has been associated with poor prognosis in breast cancer patients; it was related to the level of immune infiltration, particularly in patients with BLBC." (PMID 40862714, 2025). "ITPR1 antibodies seem to be associated with breast cancer although reports of malignancy types were more variable." (PMID 34489848, 2021). "High expression of EGOT was associated with favorable OS and RFS) in breast cancer patients, while loss of ITPR1 indicated worse RFS in the HMUCC cohort." (PMID 30999914, 2019). "Similarly, loss of ITPR1 was associated with poor RFS in breast cancer patients treated with paclitaxel in the HMUCC cohort." (PMID 30999914, 2019). "Breast cancer patients with high levels of ITPR1 mRNA have high OS (HR = 0.65, 95% CI: 0.53–0.81, P = 9e-05), RFS (HR = 0.68, 95% CI: 0.61- 0.76, P = 5.4e-12) and DMFS (HR = 0.7, 95% CI: 0.58–0.85, P = 0.00032)." (PMID 35313846, 2022). "And in GEPIA and Bc-GenExMiner v4.3, the expression level of ITPR1 in breast cancer tissues is lower than normal tissues." (PMID 35313846, 2022). "After that, we continued to use western blot to verify the expression of ITPR1 in breast cancer tissues and cells." (PMID 35313846, 2022). "Breast cancer patients with elevated expression of ITPR1 had better overall survival, recurrence-free survival, disease-specific survival, and survival without distant metastasis." (PMID 35313846, 2022). "Our analysis also showed that the expression of ITPR1 was related to immune infiltration, and the biological function of ITPR1 in breast cancer was unclear." (PMID 35313846, 2022). "So we suspect that high expression of ITPR1 can increase the sensitivity of breast cancer chemotherapy." (PMID 35313846, 2022). "After verifying the mRNA expression of ITPR1 in breast cancer, we continued to explore the protein expression of ITPRI in breast cancer through the Human Protein Atlas." (PMID 35313846, 2022). "ITPR1 is a key gene for autophagy, but its biological function is still unclear, and there are few studies on the correlation between ITPR1 gene expression and the occurrence and development of breast cancer." (PMID 35313846, 2022). "Then, we discussed the predictive value of ITPR1 expression level for clinical treatment of breast cancer." (PMID 35313846, 2022). "Predicting that breast cancer patients with high expression of ITPR1 combined with co-expressed genes will have high OS and RFS, which was more meaningful than analyzing the prognosis of co-expressed genes alone." (PMID 35313846, 2022). "Next, our research provided a new perspective on the potential function of ITPR1 in breast cancer immunology and its application as a cancer biomarker." (PMID 35313846, 2022). "After that, we continued to explore the correlation between ITPR1 and the clinicopathological characteristics of breast cancer patients." (PMID 35313846, 2022). "The expression of ITPR1 in analysis of 145 cases of breast cancer and 30 cases of adjacent normal tissue was detected by Immunohistochemistry." (PMID 35313846, 2022). "According to the survival curve of different datasets of ITPR1 expression, the prognostic value of breast cancer was analyzed with PrognoScan database." (PMID 35313846, 2022). "Bc-GenExMiner v4.3 software was used to evaluate the expression of ITPR1 in clinical and pathological features in patients with breast cancer." (PMID 35313846, 2022). "Then, we continued to explore the predictive value of ITPR1 expression level for the clinical treatment of breast cancer." (PMID 35313846, 2022). "As we shown, ITPR1 was beyond detection in breast cancer tissues, but was moderately expressed in normal tissues." (PMID 35313846, 2022). "And the Western Blot was used to detect the expression of ITPR1 between breast cancer tissues and cells." (PMID 35313846, 2022).
breast carcinoma (continued). "EGOT, an antisense intronic lncRNA derived from lncRNA ITPR1, promoted autophagy to sensitize paclitaxel cytotoxicity in breast cancers by upregulating ITPR1 expression through RNA–RNA and RNA–protein interactions." (PMID 33050642, 2020). "Thus, we assessed the correlation between ITPR1 and the level of breast cancer immune invasion from the TIMER database." (PMID 35313846, 2022). "At the same time, in order to explore the relationship between ITPR1 expression and the prognosis of breast cancer patients, we separately assessed the effects of ITPR1 expression and clinical results on overall survival and progression-free survival of breast cancer." (PMID 35313846, 2022). "Taken together, our results indicate that ITPR1 is under-expressed in patients with breast cancer." (PMID 35313846, 2022). "Using the survival meta-analysis software PrognoScan to draw survival curves with different survival information, breast cancer patients with ITPR1 (red) were positively correlated with overall survival, distant metastasis free survival, relapse free survival, disease-specific survival." (PMID 35313846, 2022). "ITPR1 was highly expressed in ER and PR-positive breast cancer patients (P < 0.0001)." (PMID 35313846, 2022). "In addition, we used the Kaplan–Meier plotter to verify the prognostic value of ITPR1 mRNA expression in patients with breast cancer." (PMID 35313846, 2022). "The expression of ITPR1 was related to the clinicopathological characteristics of breast cancer." (PMID 35313846, 2022). "However, the systematic analysis of ITPR1 in breast cancer is still rare, and the relationship between the expression of ITPR1 and the survival of breast cancer patients is unclear." (PMID 35313846, 2022). "All research results indicated that ITPR1 might affect breast cancer prognosis and participate in immune regulation." (PMID 35313846, 2022). "This study comprehensively studied the expression of ITPR1 in patients with breast cancer." (PMID 35313846, 2022). "Besides, we further explored the mechanism by which ITPR1 expression affects the prognosis of breast cancer." (PMID 35313846, 2022). "Furthermore, we used the Kaplan–Meier plotter to analyze the prognostic value of ITPR1 and co-expressed genes in patients with breast cancer." (PMID 35313846, 2022). "In addition, the expression of ITPR1 was positively correlated with related gene markers of immune cells in different types of breast cancer, especially with BRCA basal tissue breast cancer." (PMID 35313846, 2022). "Compared with normal breast tissue, the expression of ITPR1 in breast cancer is lower." (PMID 35313846, 2022). "Compared with normal breast samples, ITPR1 was significantly lower in patients with breast cancer." (PMID 35313846, 2022). "These correlations might suggest the possible mechanism of ITPR1 regulating breast cancer immune cell function, and provided preliminary guidance for the selection of therapeutic targets." (PMID 35313846, 2022). "Furthermore, examination of CCLE data also revealed that EGOT expression was positively correlated with ITPR1 mRNA expression in human breast cancer cell lines and other cancer cell lines." (PMID 30999914, 2019). "In short, ITPR1 might be a potential target for breast cancer therapy." (PMID 35313846, 2022). "These further proved that ITPR1 could improve the prognosis of breast cancer patients." (PMID 35313846, 2022). "Therefore, the expression of ITPR1 gene might be a new biomarker factor affecting the prognosis of breast cancer." (PMID 35313846, 2022). "Concerning breast cancer, alcohol-induced genes BRAF and ITPR1 presented a higher expression in ER+ breast cancer patients with a higher alcohol intake." (PMID 39125744, 2024). "After analyzing the expression of ITPR1 and the prognostic value of breast cancer patients, we used STRING's "co-expression" module to analyze 20 co-expressed genes that were significantly related to ITPR1." (PMID 35313846, 2022).